GLP1R (glucagon like peptide 1 receptor)
Diseases named in the same sentence as GLP1R in open-access papers (continued):
Sharing a sentence is not in itself a finding about the gene and the disease.
type 2 diabetes (continued). "This systematic review evaluates the cardiovascular effects of glucagon-like peptide-1 receptor agonists (GLP-1 RAs) in adults with type 2 diabetes mellitus (T2DM) and established atherosclerotic cardiovascular disease, chronic kidney disease, or heart failure (HF)." (PMID 40918811, 2025). "Glucagon-like peptide-1 receptor agonists (GLP-1RAs), originally developed for type 2 diabetes and obesity, have recently emerged as promising modulators of reward-related brain circuits." (PMID 40843757, 2025). "Background/Objectives: Glucagon-like peptide-1 receptor agonists (GLP-1RAs), which were originally developed for managing type 2 diabetes by enhancing insulin secretion and reducing appetite, have emerged as promising candidates in alcohol use disorder (AUD)." (PMID 40722294, 2025). "The emergence of glucagon-like peptide-1 receptor agonists (GLP-1RAs), including tirzepatide (Mounjaro), has revolutionized the management of type 2 diabetes mellitus and obesity." (PMID 40225446, 2025). "Glucagon-like peptide-1 receptor agonists (GLP-1RAs), originally developed for type 2 diabetes, have recently emerged as promising candidates for addiction treatment." (PMID 41552827, 2025). "Tirzepatide, a novel dual incretin analogue targeting both GLP-1R and GIP receptor (GIPR), has been approved for the treatment of type 2 diabetes and obesity." (PMID 40517248, 2025). "Recently, GLP-1 receptor (GLP-1R) and its agonists have garnered widespread attention in the medical community because they are highly potent treatments for obesity and type 2 diabetes." (PMID 40494889, 2025). "The glucagon-like peptide 1 receptor (GLP-1R) analog semaglutide, a once-weekly injectable medication for type 2 diabetes mellitus and obesity, targets the circumventricular organs rather than permeating the blood-brain barrier." (PMID 38454010, 2025). "This review examines the therapeutic potential of glucagon-like peptide-1 receptor agonists (GLP-1RAs), medications approved for type 2 diabetes and obesity now being investigated for eating disorders through their modulation of metabolic and reward pathways." (PMID 41303457, 2025). "Glucagon-like peptide-1 receptor agonists (GLP-1RAs), widely used in the management of type 2 diabetes and obesity, have shown potential to support muscle mass and function through pleiotropic mechanisms." (PMID 40869417, 2025). "This systematic review and meta-analysis evaluated the impact of glucagon-like peptide-1 receptor agonists (GLP-1RAs) on hepatocellular carcinoma (HCC) and liver decompensation in patients with type 2 diabetes." (PMID 39937048, 2025). "Semaglutide, a glucagon-like peptide-1 receptor agonist (GLP-1RA) known for its glucose-lowering and weight-reducing effects, has been linked to reduced cardiovascular disease (CVD) risk in patients with type 2 diabetes (T2D)." (PMID 40225492, 2025). "Patients with type 2 diabetes mellitus (T2DM) initiating treatment with glucagon-like peptide-1 receptor agonists (GLP-1RAs) may encounter various risks and complications." (PMID 41054590, 2025). "Glucagon-like peptide-1 receptor agonists (GLP-1RAs), such as semaglutide, are widely used in the treatment of metabolic disorders, including type 2 diabetes (T2D) and obesity." (PMID 40309769, 2025). "Background/Objectives: Glucagon-like peptide-1 receptor agonists (GLP-1RAs) are increasingly prescribed for people living with obesity and type 2 diabetes due to their efficacy in reducing appetite and body weight." (PMID 41373949, 2025). "The safety profile of Glucagon-Like Peptide-1 receptor agonists (GLP-1 RAs), including liraglutide, is of significant clinical relevance as these agents are increasingly used not only for type 2 diabetes but also for obesity management." (PMID 40565353, 2025).
type 2 diabetes (continued). "Glucagon-like peptide-1 receptor agonists (GLP-1RAs), such as tirzepatide (Mounjaro), are widely used for type 2 diabetes and obesity, but their effects on drug metabolism and immune regulation remain areas of concern." (PMID 40225446, 2025). "Glucagon-like peptide-1 receptor agonists (GLP-1RAs), initially developed for type 2 diabetes, have shown promise in addressing AIWG by reducing weight, improving metabolic parameters, and offering potential neuroprotective and psychiatric benefits." (PMID 41091899, 2025). "Glucagon-like peptide 1 receptor agonists (GLP-1 RAs) have become indispensable for both patients and clinicians in managing type 2 diabetes mellitus (T2DM) and obesity." (PMID 40699685, 2025). "Glucagon-like peptide-1 receptor agonists (GLP1-RAs) have emerged as a transformative class of medications, initially developed for the management of type 2 diabetes mellitus (T2DM)." (PMID 41071055, 2025). "Glucagon-like peptide-1 receptor agonists (GLP-1RAs) are primarily used for treating obesity and managing type 2 diabetes." (PMID 40652274, 2025). "Glucagon-like peptide-1 receptor (GLP1R) agonists, GLP1 analogues that are resistant to degradation by dipeptidyl peptidase 4, are used to treat type 2 diabetes mellitus (T2DM)." (PMID 40770700, 2025). "Glucagon-like peptide-1 receptor agonists (GLP-1RAs), such as semaglutide and tirzepatide, have emerged as transformative agents for type 2 diabetes and obesity through their potent effects on weight reduction, insulin sensitivity, and cardiovascular outcomes." (PMID 41479489, 2025). "Within this framework, glucagon-like peptide-1 receptor agonists (GLP-1RAs), initially developed for the treatment of type 2 diabetes and obesity, have been identified as promising candidates for modulating the neural circuits involved in addiction." (PMID 40843757, 2025). "Glucagon-like peptide-1 receptor agonists (GLP-1RAs), initially developed for type 2 diabetes and obesity, have evolved into multi-organ potential therapeutics due to their pleiotropic effects beyond glycemic control." (PMID 41019986, 2025). "Background/Objectives: Despite the established cardiovascular benefit of sodium–glucose cotransporter-2 inhibitors (SGLT2is) and glucagon-like peptide-1 receptor agonists (GLP-1RAs), these medications are under-prescribed in patients with type 2 diabetes." (PMID 40217621, 2025). "Semaglutide, a glucagon-like peptide-1 receptor agonist (GLP-1RA), has demonstrated substantial efficacy in managing type 2 diabetes mellitus (T2DM)." (PMID 41302309, 2025). "GLP‐1R expression in the lateral hypothalamic nucleus decreases in patients with body mass index (BMI) more than 25 kg/m2, and GLP‐1R expression in PVN and ARC decreases in patients with type 2 diabetes mellitus." (PMID 39661011, 2025). "New pharmacotherapies, such as glucagon-like peptide-1 receptor agonists (GLP-1RAs), have recently emerged for treatment of both type 2 diabetes and obesity." (PMID 40932823, 2025). "Glucagon-like peptide-1 receptor agonists (GLP-1RAs) are established treatments for type 2 diabetes mellitus (T2DM), improving glycaemic control through multiple mechanisms, including enhanced insulin secretion, delayed gastric emptying, and appetite suppression." (PMID 41516966, 2025). "Liraglutide (LIRA), a glucagon-like peptide-1 receptor (GLP-1R) agonist, is currently employed in the treatment of type 2 diabetes mellitus and obesity." (PMID 41304982, 2025). "Glucagon-like peptide-1 receptor agonists (GLP-1RAs), widely used for managing type 2 diabetes (T2D) and weight, are gaining attention for treatment of a broad set of conditions." (PMID 40832397, 2025). "Tirzepatide (LY3298176) is the first peptide dual agonist for type 2 diabetes mellitus (T2DM), which targets both GIPR and GLP1R." (PMID 38987789, 2024). "Glucagon-like Peptide 1 Receptor (GLP1-R) agonists, used in type 2 diabetes treatment, exhibit neuroprotective effects in various brain injury models, including HIE." (PMID 38783166, 2024).
type 2 diabetes (continued). "Glucagon-like peptide-1 receptor agonist (GLP-1RA), a novel hypoglycemic agent for the treatment of type 2 diabetes, has well-known effects such as lowering blood sugar, ameliorating inflammation, reducing weight, and lowering blood lipids." (PMID 39371922, 2024). "Glucagon-like peptide-1 receptor agonists (GLP-1RAs), initially developed for type-2 diabetes management, have emerged as powerful tools in obesity treatment." (PMID 39796706, 2024). "Regarding new treatment approaches, cardiovascular outcome trials in patients with type 2 diabetes have demonstrated the effectiveness of sodium-glucose cotransporter 2 (SGLT2) inhibitors and glucagon-like peptide 1 receptor agonists (GLP1RA)." (PMID 39338165, 2024). "This indicates the potential of changes in triacylglycerol composition to impact GLP-1R and GIPR activities, thereby increasing the onset of type 2 diabetes directly or indirectly within this patient group." (PMID 38614123, 2024). "GLP-1 receptor (GLP-1R) agonists are synthetic products that have similar effects to GLP-1 but are less prone to degradation, and they are widely used in the treatment of type 2 diabetes and obesity." (PMID 39858999, 2024). "The first glucagon-like peptide-1 receptor agonists (GLP-1RAs) to be approved for preadolescent and adolescent populations was liraglutide in 2019, which treated type 2 diabetes (T2D)." (PMID 39412809, 2024). "The results of this trial highlight the potential of the novel GCGR/GLP-1R dual agonist survodutide for the treatment of NASH, type 2 diabetes and obesity." (PMID 38095657, 2024). "In placebo-controlled trials of type 2 diabetes patients with moderate to severe CKD, GLP-1R agonists significantly slowed the decline in eGFR." (PMID 38540270, 2024). "The peptide GLP1R and glucagon receptor agonist ZP2495 improved contractility of the heart and inhibited cardiomyocyte apoptosis in diabetic mice db/db (type 2 diabetes) with CAO and reperfusion." (PMID 38732142, 2024). "This study aimed to explore the risk factors for gastrointestinal side effects (GISEs) in patients with type 2 diabetes mellitus (T2DM) during treatment with glucagon-like peptide-1 receptor agonists (GLP-1RAs) based on real-world data and to develop a prediction model for GLP-1RA-related GISEs." (PMID 39717105, 2024). "Glucagon-like peptide-1 receptor agonists (GLP-1RAs) are an increasingly prevalent class of drugs for managing overweight/obesity and type 2 diabetes mellitus." (PMID 39221363, 2024). "In recent years, glucagon-like peptide 1 receptor agonists (GLP-1-RAs) have become commonly used pharmacotherapies for obesity and type 2 diabetes." (PMID 38315575, 2024). "The dual activation of glucagon-like peptide-1 receptor (GLP-1R) and glucose-dependent insulinotropic polypeptide receptor (GIPR) has emerged as a promising therapeutic strategy for managing type 2 diabetes and obesity." (PMID 39030216, 2024). "In contrast, small molecule GLP‐1R non‐peptide agonists, such as Boc5 and WB4‐24,40 are still under investigation to confirm their effectiveness in treating type 2 diabetes mellitus." (PMID 38926763, 2024). "The use of glucagon-like peptide-1 receptor agonists (GLP-1RAs), a class of drugs approved for treating type 2 diabetes, has been explored in patients with NAFLD." (PMID 38117293, 2024). "Glucagon-like peptide-1 receptor agonists (GLP-1RA) are effective to treat adult and pediatric populations with type 2 diabetes (T2D) and/or obesity, and they have an established safety profile." (PMID 39906033, 2024). "Glucagon-like peptide-1 receptor (GLP-1R) agonists, including semaglutide, were initially approved by the U.S. FDA for the treatment of type 2 diabetes yet are now available for chronic weight management." (PMID 38878250, 2024).
type 2 diabetes (continued). "In year 2020, the Diabetes Canada guidelines recommended use of new classes, namely sodium-glucose co-transporter 2 (SGLT-2) inhibitors and glucagon-like peptide-1 receptor (GLP-1) agonist, as preferred second-line pharmaceutical agents for type 2 diabetes." (PMID 39146274, 2024). "In recent years, the kidney effects of incretin-based therapies, particularly glucagon-like peptide-1 receptor agonists (GLP-1RAs), have garnered substantial interest in the management of type 2 diabetes and obesity." (PMID 38477666, 2024). "GLP-1R agonists (GLP-1RA) are utilized clinically for the treatment of type 2 diabetes (T2D) and obesity and a single GIP receptor–GLP-1 receptor (GIPR–GLP-1R) coagonist, tirzepatide (TZP), is approved for the treatment of T2D and obesity." (PMID 39723966, 2024). "GLP-1R, glucagon receptor (GCGR) and glucose-dependent insulinotropic polypeptide receptor (GIPR) are validated therapeutic targets for type 2 diabetes and obesity." (PMID 38346960, 2024). "Over the past decade, glucagon-like peptide-1 receptor agonists (GLP-1RAs) have emerged as highly effective agents for reducing both blood glucose levels and body weight in individuals with type 2 diabetes (T2D), obesity, or both." (PMID 39595069, 2024). "Interestingly, a decreased expression of GLP-1R was reported in the lateral hypothalamic area in patients with a body mass index (BMI) ≥ 25 kg/m2 and in the paraventricular and infundibular (arcuate) hypothalamic nuclei in patients with type 2 diabetes mellitus." (PMID 38463533, 2024). "Glucagon-like peptide-1 receptor agonists (GLP-1RAs) have garnered considerable attention for the management of overweight/obesity and type 2 diabetes mellitus." (PMID 39221363, 2024). "GLP-1R, GCGR and GIPR are essential regulators of glucose homeostasis and therapeutic targets for type 2 diabetes and obesity." (PMID 38346960, 2024). "Few studies explored the effect of the combination of glucose sodium-cotransporter-2 inhibitors (SGLT-2i) and glucagon-like peptide-1 receptor agonists (GLP-1RA) on the incidence of cardiovascular events in patients with type 2 diabetes (T2D) and acute myocardial infarction (AMI)." (PMID 38184582, 2024). "Exenatide belongs to the glucagon-like peptide-1 receptor agonist (GLP-1RA) group and is used in diabetes mellitus type 2 treatment." (PMID 36902639, 2023). "The development of single-molecule co-agonists for the glucagon-like peptide-1 (GLP-1) receptor (GLP-1R) and glucose-dependent insulinotropic polypeptide (GIP) receptor (GIPR) is considered a breakthrough in the treatment of obesity and type 2 diabetes." (PMID 37946085, 2023). "We thus aimed to develop genetic instruments for the targets of five approved type 2 diabetes medications with known mechanisms of action (sulfonylurea receptor 1 [ATP binding cassette subfamily C member 8 (ABCC8)], PPARG, SGLT2, DPP4 and GLP1R)." (PMID 37171501, 2023). "Glucagon-like peptide-1 receptor agonists (GLP-1 RAs), a drug used to treat type 2 diabetes, have been shown to have neuroprotective effects." (PMID 37771725, 2023). "Liraglutide, a glucagon-like peptide 1 receptor (GLP-1R) agonist, is a novel hypoglycemic agent recommended by the latest guidelines for treating type 2 diabetes and comorbid ASCVD due to its proven cardiovascular benefits." (PMID 37278349, 2023). "Glucagon-like peptide-1 receptor agonists (GLP1RA) have been transformative for patients and clinicians in treating type-2 diabetes and obesity." (PMID 38201269, 2023). "Incretin-based therapies, particularly glucagon-like peptide-1 receptor agonists (GLP-1 RAs), have demonstrated cardiovascular benefits in people with type 2 diabetes." (PMID 37433896, 2023). "We employed the keywords "Type 2 diabetes OR T2DM or diabetes" AND "Tirzepatide OR LY3298176 OR twincretin OR dual glucose-dependent insulinotropic polypeptide and glucagon-like peptide-1 receptor agonist" AND "randomized controlled trial"." (PMID 37779743, 2023).
type 2 diabetes (continued). "Inhibitors of the sodium-glucose cotransporter 2 (SGLT2i) and glucagon-like peptide-1 receptor agonists (GLP-1 RA) have been studied and trialled in type 2 diabetes with an overwhelming body of evidence supporting their use in type 2 diabetes." (PMID 37505282, 2023). "Exendin-4 (Ex-4), a glucagon-like peptide 1-receptor (GLP-1R) agonist, approved for adult type 2 diabetes treatment, has been shown to be protective towards BBB integrity by inhibiting MMP-9 in a rat model of ischemic stroke." (PMID 37240207, 2023). "Recently, glucagon-like peptide 1 receptor agonists (GLP-1RAs), a class of drugs used to treat type 2 diabetes and obesity, have shown therapeutic effects against NAFLD." (PMID 37298276, 2023). "This study investigated the effect of a combination of glucagon-like peptide-1 receptor agonist (GLP-1 RA) and basal insulin (BI) in poorly controlled type 2 diabetes mellitus previously treated with premixed insulin." (PMID 36897731, 2023). "Several multi-targeting agonists at GIPR, GLP-1R or GCGR, developed to maximize metabolic benefits with reduced side-effects, are in clinical trials to treat type 2 diabetes and obesity." (PMID 35217653, 2022). "Accumulating evidence supports the early use of glucagon-like peptide-1 receptor agonists (GLP-1RAs) and sodium glucose transporter-2 inhibitors (SGLT-2is) for the treatment of type 2 diabetes." (PMID 35265043, 2022). "GLP-1R is widely expressed and GLP-1 is now understood to be a pleiotropic hormone with therapeutic potential beyond type 2 diabetes mellitus." (PMID 35745639, 2022). "For example, the glucagon-like peptide-1 receptor agonists (GLP-1RAs), which were used for the treatment of type 2 diabetes, have been modified by several FAs to prolong the circulation half-life." (PMID 36393853, 2022). "Glucagon-like peptide-1 receptor agonists (GLP-1RAs) were developed as insulinotropic and anti-hyperglycemic agents for the treatment of type 2 diabetes, but their neurotrophic and neuroprotective activities have been receiving increasing attention." (PMID 35874814, 2022). "Actually, therapeutic agents such as GLP-1R agonists (GLP-1RAs) and DPP-IV inhibitors are largely employed in the treatment of type 2 diabetes and obesity." (PMID 36293281, 2022). "Novel anti-diabetic agents, sodium-glucose co-transporter 2 inhibitors (SGLT-2i) and glucagon-like peptide-1 receptor agonists (GLP-1RA), have shown promising effects on cardiovascular protection in patients with type 2 diabetes." (PMID 36176438, 2022). "Therefore, after some biomedical modifications for achieving enhanced therapeutic efficiency and sustained effects, GLP-1R agonists have been widely used in the clinical treatment of type 2 diabetes mellitus (T2DM) as well as clinical evaluation of obesity." (PMID 35510038, 2022). "Other metabolic-related drugs are glucagon-like peptide-1 receptor (GLP-1R) agonists, which have been approved to treat obesity and type 2 diabetes." (PMID 35754743, 2022). "According to research, GLP-1R agonists (GLP-1RAs) have a greater impact on hemoglobin A1c (HbA1c), fasting plasma glucose (FPG), blood lipids, and body weight in patients with type 2 diabetes than DPP4 inhibitors." (PMID 35736482, 2022). "Glucagon-like peptide-1 receptor agonists (GLP-1 RAs), one of the classes of antihyperglycemic drugs, have been recommended to manage type 2 diabetes mellitus (T2DM)." (PMID 35371594, 2022). "Recent evidence demonstrates that glucose-lowering medications, such as glucagon-like peptide 1 receptor agonists and sodium-glucose cotransporter-2 inhibitors, are of particular benefit in the prevention and treatment of CKD in patients with type 2 diabetes." (PMID 35289751, 2022). "Recently, tirzepatide, a dual GLP-1R and GIP receptor agonist, is undergoing clinical trials for the treatment of type 2 diabetes." (PMID 35745639, 2022).